ARCN1 (archain 1 coat protein complex I subunit delta)
Description:
Component of the coatomer, a cytosolic protein complex that binds to dilysine motifs and reversibly associates with Golgi non-clathrin-coated vesicles, which further mediate biosynthetic protein transport from the ER, via the Golgi up to the trans Golgi network. The coatomer complex is required for budding from Golgi membranes, and is essential for the retrograde Golgi-to-ER transport of dilysine-tagged proteins. In mammals, the coatomer can only be recruited by membranes associated to ADP-ribosylation factors (ARFs), which are small GTP-binding proteins; the complex also influences the Golgi structural integrity, as well as the processing, activity, and endocytic recycling of LDL receptors (By similarity).
Synonyms: Delta-COP; COPD; SRMMD; SSMG
Tractability: Antibody: UniProt places it where antibodies can reach, with medium confidence. PROTAC: ubiquitination databases record sites on it; its protein half-life has been measured.
Gene: Protein-coding gene on chromosome 11 (118,572,390 to 118,603,033, forward strand). Ensembl gene ENSG00000095139.
Subcellular location: Cytoplasm; Golgi apparatus membrane; Cytoplasmic vesicle, COPI-coated vesicle membrane
Subcellular location (Human Protein Atlas): Vesicles; Cytosol; Golgi apparatus
Pathways (Reactome):
Vesicle-mediated transport: COPI-dependent Golgi-to-ER retrograde traffic; COPI-mediated anterograde transport
Gene Ontology:
Molecular function: protein binding; RNA binding; structural molecule activity
Biological process: endoplasmic reticulum to Golgi vesicle-mediated transport; Golgi localization; intracellular protein transport; retrograde vesicle-mediated transport, Golgi to endoplasmic reticulum
Cellular component: membrane; COPI vesicle coat; cytosol; endoplasmic reticulum membrane; Golgi membrane; transport vesicle; COPI-coated vesicle; COPI-coated vesicle membrane; cytoplasm; cytoplasmic vesicle; endoplasmic reticulum; Golgi apparatus
Genetic constraint (gnomAD): Loss-of-function variants: 3 observed, 53.3 expected, observed/expected ratio (o/e) 0.0563, 90% interval 0.025 to 0.14. The upper end of that interval is the gene's LOEUF score, 0.14, which puts it in group 1 of 6, group 1 being the genes least tolerant of losing a copy. Missense variants: 397 observed, 570.47 expected, observed/expected ratio (o/e) 0.7, 90% interval 0.64 to 0.76. Synonymous variants: 196 observed, 200.44 expected, observed/expected ratio (o/e) 0.98, 90% interval 0.87 to 1.1.
Homologues: Orthologues: chimpanzee ARCN1 (99% identical), macaque ARCN1 (99% identical), mouse Arcn1 (99% identical), rat Arcn1 (99% identical), dog ARCN1 (99% identical), guinea pig ARCN1 (99% identical), pig ARCN1 (99% identical), tropical clawed frog arcn1 (88% identical), zebrafish arcn1a (83% identical), zebrafish arcn1b (82% identical), Drosophila melanogaster deltaCOP (61% identical), Caenorhabditis elegans copd-1 (51% identical).
Diseases named in the same sentence as ARCN1 in open-access papers:
ARCN1 is named in the same sentence as 32 diseases in open-access papers, as found by Europe PMC text mining. Sharing a sentence is not in itself a finding about the gene and the disease. The quoted sentences say what the papers report.
Ataxia (3 papers, 2010 to 2025). Ataxia refers to impaired coordination of voluntary muscle movement. "Mice with a homozygous missense mutation in Arcn1 showed several similarities to the individuals with ARCN1-related syndrome, such as low body weight and neurological phenotype, including ataxia due to cerebellar degeneration." (PMID 40552310, 2025). "Here we show that a mutation in Arcn1 is responsible for the phenotypes in an ENU-induced mouse mutant, nur17, which was identified by screening for mice with both diluted coat color and ataxia." (PMID 20502676, 2010).
breast carcinoma (3 papers, 2016 to 2021). "The importance of ARCN1 for tumor progression is further confirmed by the association of high ARCN1 expression with the poor survival of gastric cancer patients and patients with HER2-positive breast cancer." (PMID 28223711, 2017). "One of the four potential gene targets of miR-361-5p in breast cancer, ARCN1 was found in our HiSeq V2 gene expression analysis to be significantly correlated with poor patient survival." (PMID 27959953, 2016). "Furthermore, the analysis of ARCN1 expression in human tumors shows that higher levels of ARCN1 expression correlates with lower survival rate of gastric, ovarian, and HER+ positive breast cancer patients." (PMID 28223711, 2017).
developmental delay (3 papers, 2021 to 2025). "While mutations in ARCN1 have been associated with craniofacial dysmorphism and developmental delay, and DNA2 variants with mitochondrial myopathy and external ophthalmoplegia, neither variant was deemed causative in this case due to several reasons." (PMID 40918659, 2025). "Mutations in ARCN1 give rise to a syndromic disorder with rhizomelic short stature with microretrognathia and developmental delay." (PMID 38044464, 2024). "Interestingly, loss-of-function mutations in ARCN1 (which encodes δ-COP) cause a distinctive syndrome of craniofacial abnormalities, microcephalic dwarfism and mild developmental delay (MIM # 617164)." (PMID 33632302, 2021). "ARCN1-related syndrome (δ-COP) also includes features of microcephaly and, albeit milder, developmental delay." (PMID 33632302, 2021).
epithelial ovarian cancer (1 paper, 2015). "These cumulative observations indicate that limiting expression of ARCN1 is a common vulnerability in both epithelial ovarian cancer and non‐small cell lung cancer lines that can be artificially perturbed by miR‐517a (Fig EV6B)." (PMID 26655797, 2015).
glioma (1 paper, 2012). A benign or malignant brain and spinal cord tumor that arises from glial cells (astrocytes, oligodendrocytes, ependymal cells). "The second novel locus was within the ARCN1 gene, and it was associated with a significantly reduced risk for glioma." (PMID 23300798, 2012). "Further logistic regression analyses revealed that patients with the rs7115634 G allele in the ARCN1 gene had a 21% reduction of glioma risk (adjusted OR = 0.79, 95%CI = 0.70–0.89, P = 2.12×10−4)." (PMID 23300798, 2012). "Our data strongly support PHLDB1 as a susceptibility gene for glioma, also shedding light on a new potentially candidate gene, ARCN1." (PMID 23300798, 2012). "Additionally, we found two novel independent SNPs (rs7115634 and 2236661) in the PHLDB1 gene and one SNP (rs494560) in the ARCN1 gene that conferred to glioma risk." (PMID 23300798, 2012). "It is possible that all identified SNPs (rs17748 in the 3′UTR, rs7115634, rs2236661 and rs494560 in introns) in this region affect glioma risk by modulating PHLDB1 and ARCN1 expression levels or function." (PMID 23300798, 2012). "Nevertheless, it is worth noting that the three newly identified variants (rs7115634 in ARCN1, rs2236661 and rs494560 in PHLDB1) and the rs17748 SNP contributed to a cumulative risk effect for glioma susceptibility." (PMID 23300798, 2012). "Two separate clusters of glioma-associated SNPs were found, including the previously reported PHLDB1 locus and a novel locus (ARCN1)." (PMID 23300798, 2012). "However, the exact mechanism of the ARCN1 gene in the development of glioma still needs further investigation." (PMID 23300798, 2012).
influenza (1 paper, 2018). An acute viral infection of the respiratory tract, occurring in isolated cases, in epidemics, or in pandemics; it is caused by serologically different strains of viruses (influenzaviruses) designated A, B, and C, has a 3-day incubation period, and usually lasts for 3 to 10 days. "While RNAi of a single gene (e.g. ATP6AP1, COPA, or ARCN1) inhibited replication of many strains of influenza tested here, there were several endemic strains that were not inhibited, and inhibition of diverse strains (e.g. H7N3, H9N2) was particularly weak in the absence of combinatorial RNAi." (PMID 29775471, 2018).
lung carcinoma (1 paper, 2015). "Notably, direct ARCN1 depletion phenocopied the miR‐517a toxicity profile in both ovarian and lung cancer cell lines, suggesting ARCN1 function is limiting in a large cohort of cancer cells and can be artificially targeted by miR‐517a." (PMID 26655797, 2015).
neuroblastoma (1 paper, 2012). Neuroblastoma (NB) is the most common solid, extracranial childhood tumor. "This newly identified maker SNP is mapped to the intron of ARCN1, which is located within the commonly deleted region of neuroblastoma patients at human chromosome 11q23.3." (PMID 23300798, 2012).
infection (10 papers, 2011 to 2025). The state of being infected such as from the introduction of a foreign agent such as serum, vaccine, antigenic substance or organism. "Both Western blot and grayscale analysis showed that ARCN1 knockdown markedly increased IKKε protein abundance upon infection, accompanied by elevated phosphorylation of IRF3, STAT1, and STAT2." (PMID 41343552, 2025). "Upon infection, ARCN1 exhibited pronounced ER colocalization and moderate Golgi colocalization, whereas IKKε was likewise enriched at the ER with comparatively weaker Golgi colocalization." (PMID 41343552, 2025). "Immunofluorescence analysis of RSV-L19–mCherry infection further demonstrated a marked decrease in RSV-positive cells following ARCN1 knockdown, indicating reduced viral load." (PMID 41343552, 2025). "The results showed that RSV-L19 infection significantly increased ARCN1 and IKKε protein levels, whereas STUB1 expression remained unchanged." (PMID 41343552, 2025). "Consistently, Co-IP analysis showed that the interaction between endogenous STUB1 and IKKε was markedly reduced in ARCN1-knockdown RAW264.7 cells following 12 h of RSV-L19 infection (MOI = 10)." (PMID 41343552, 2025). "The results confirmed that RSV-L19 infection significantly upregulated ARCN1 protein and mRNA levels in both macrophage populations." (PMID 41343552, 2025). "ARCN1 is lowly expressed in developing human cortex tissue, but after infection by SARS-CoV-2, we found a 15% increase in expression, exclusively in infected cells coexpressing dsRNA." (PMID 35858406, 2022). "In contrast, while infection by the flavivirus Dengue virus 2 (DENV2) was inhibited by clathrin or ARCN1 depletion and was dependent on endosomal acidification (data not shown), it was resistant to depletion of either FUZ or TSPAN9." (PMID 24367265, 2013). "To assess whether this regulation is cell-type independent, we modulated ARCN1 expression in HEK293T cells before RSV-L19 infection (MOI = 10)." (PMID 41343552, 2025). "However, ARCN1 expression remained largely unchanged in HEp-2 cells after RSV-L19 infection, suggesting that RSV-induced ARCN1 upregulation is cell type-specific." (PMID 41343552, 2025). "Importantly, compared with wild-type (WT) mouse PMs, ARCN1 expression in IFN-I receptor–deficient (IFNAR1 − /−) mouse PMs was not significantly upregulated following RSV-L19 infection." (PMID 41343552, 2025). "This endogenous interaction was confirmed in RAW264.7 cells and was significantly enhanced 12 h after RSV-L19 infection (MOI = 10), suggesting that ARCN1-IKKε interaction is more active during RSV infection." (PMID 41343552, 2025). "Depletion of clathrin, ARCN1, FUZ or TSPAN9 significantly inhibited infection by both viruses, thus demonstrating a requirement for these proteins during alphavirus infection of primary human cells." (PMID 24367265, 2013). "Our data demonstrated that ARCN1 depletion blocked alphavirus-cell binding, and identified two novel host factors, FUZ and TSPAN9, that promote alphavirus entry and infection." (PMID 24367265, 2013). "Furthermore, Co-IP and Western blot revealed a markedly enhanced interaction between ARCN1, STUB1, and IKKε in both RAW264.7 cells and PMs following RSV-L19 infection (MOI = 10) compared with uninfected controls." (PMID 41343552, 2025). "Following RSV-L19 infection (MOI = 10), ARCN1 overexpression did not alter RSV-F transcript levels, indicating no discernible impact on epithelial viral burden." (PMID 41343552, 2025). "ARCN1 overexpression did not enhance VSV-G protein expression during VSV infection (MOI = 0.1) or RSV M2-1 and NS1 protein levels during RSV-L19 infection (MOI = 10)." (PMID 41343552, 2025).
cancer (6 papers, 2012 to 2021). A tumor composed of atypical neoplastic, often pleomorphic cells that invade other tissues. "ARCN1 has also been identified in genetic screens wherein knockdown impaired the growth of a panel of cancer cell lines as well as act as an autophagy modulator." (PMID 34725334, 2021). "Overall the results with ARCN1 confirmed our previous finding that targeting the COPI complex is a viable strategy for new cancer therapy." (PMID 28223711, 2017). "We show the association of the expression of the identified genes with development and mortality of human cancers and explore the mechanism of the effect of ARCN1 and DDX24 depletion in tumor cells." (PMID 28223711, 2017). "The gene has been highlighted as a key determinant for sensitivity to the glycolytic inhibitor 2-deoxyglucose (2DG) in cancer cells, in which ARCN1 knockdown sensitized cells to 2DG." (PMID 27959953, 2016). "Importantly, ARCN1 (δ-COP) knockdown has previously been shown to significantly impair the viability of cancer cell lines by potentiating activation of the UPR and inhibiting phosphatidylinositol 3-kinase (PI3-kinase)/Akt signalling." (PMID 34725334, 2021). "The siRNA depletion of 3 genes - ARCN1, DDX24, and RPL35A - significantly inhibited the growth of all three cancer cell lines but not normal cells." (PMID 28223711, 2017). "It is therefore not surprising that depletion of only three genes – ribosomal protein RPL35A, COPI subunit ARCN1, and RNA helicase DDX24 – selectively inhibited the growth of all three cancer cell lines without strong effects on BJ-hTERT cells." (PMID 28223711, 2017). "Interestingly, in the majority of cancer datasets available in TCGA the expression level of ARCN1 mRNA are not significantly changed relative to corresponding normal tissues suggesting that the sensitivity of cancer cells to ARCN1 depletion may not be dependent on increased ARCN1 expression." (PMID 28223711, 2017).
tumor (3 papers, 2017 to 2020). "Molecular analysis of tumor tissue revealed a ROS1:ARCN1 fusion, and therapy with a ROS1-inhibitor was therefore suggested but not feasible due to the unavailability of matching clinical studies in Europe at this time point." (PMID 33353026, 2020). "In the survival groups, ARCN1 showed a significant difference in gene expression patterns between variant carriers in the 0-2 year and 5-10 year survival groups, suggesting that ARCN1 may have a tumor suppressor effect as elevated expression thereof indicated longer survival times." (PMID 30416686, 2018). "Contrary to the depletion of COPZ1, where COPZ2 expression protects normal cells from Golgi disruption, depletion of ARCN1 disrupted the Golgi equally in normal and tumor cells." (PMID 28223711, 2017).
CNS tumors (1 paper, 2024). "Six different ROS1 fusion partners have already been described in pediatric CNS tumors (+/−7% of pediatric CNS tumors): GOPC, ARCN1, CHCHD3, ZCCHC8, TPR and CEP85L." (PMID 39409964, 2024).
ARCN1 also shares sentences with these, for which no sentence is quoted: chlamydial infection (5 papers); microcephaly (2); autoimmune disease (1); celiac disease (1); Dyskinesia (1); Dystonia (1); epilepsy (1); External ophthalmoplegia (1); gastric cancer (1); glioblastoma (1); Mitochondrial myopathy (1); mucinous ovarian carcinoma (1); Myoclonus (1); non-small cell lung carcinoma (1); osteogenesis imperfecta (1); ovarian cancer (1); pneumonia (1); Primary microcephaly (1); Tremor (1); unspecified (1).